POM121 (POM121 transmembrane nucleoporin)
Description:
Essential component of the nuclear pore complex (NPC). The repeat-containing domain may be involved in anchoring components of the pore complex to the pore membrane. When overexpressed in cells induces the formation of cytoplasmic annulate lamellae (AL).
Synonyms: KIAA0618; POM121A; DKFZP586G1822; DKFZP586P2220; P145
Tractability: Antibody: UniProt predicts a signal peptide or a membrane-spanning region. PROTAC: ubiquitination databases record sites on it; its protein half-life has been measured.
Gene: Protein-coding gene on chromosome 7 (72,879,349 to 72,951,440, forward strand). Ensembl gene ENSG00000196313.
Subcellular location: Nucleus, nuclear pore complex; Nucleus membrane; Endoplasmic reticulum membrane
Subcellular location (Human Protein Atlas): Nuclear membrane; Nucleoplasm
Pathways (Reactome):
Disease: Defective TPR may confer susceptibility towards thyroid papillary carcinoma (TPC); HCMV Early Events; HCMV Late Events; NEP/NS2 Interacts with the Cellular Export Machinery; NS1 Mediated Effects on Host Pathways; Nuclear import of Rev protein; Rev-mediated nuclear export of HIV RNA; SARS-CoV-2 activates/modulates innate and adaptive immune responses; Transport of Ribonucleoproteins into the Host Nucleus; Viral Messenger RNA Synthesis; Vpr-mediated nuclear import of PICs
Metabolism of RNA: Transport of Mature mRNA Derived from an Intronless Transcript; Transport of Mature mRNA derived from an Intron-Containing Transcript; Transport of the SLBP Dependant Mature mRNA; Transport of the SLBP independent Mature mRNA; snRNP Assembly; tRNA processing in the nucleus
Metabolism of proteins: SUMOylation of DNA damage response and repair proteins; SUMOylation of DNA replication proteins; SUMOylation of RNA binding proteins; SUMOylation of SUMOylation proteins; SUMOylation of chromatin organization proteins; SUMOylation of ubiquitinylation proteins
Metabolism: IP3 and IP4 transport between cytosol and nucleus; IP6 and IP7 transport between cytosol and nucleus; IPs transport between nucleus and cytosol; Regulation of Glucokinase by Glucokinase Regulatory Protein
Cell Cycle: Nuclear Pore Complex (NPC) Disassembly; Postmitotic nuclear pore complex (NPC) reformation
Cellular responses to stimuli: Regulation of HSF1-mediated heat shock response
Immune System: ISG15 antiviral mechanism
Gene Ontology:
Molecular function: protein binding; structural constituent of nuclear pore
Biological process: nucleocytoplasmic transport; protein import into nucleus; RNA export from nucleus
Cellular component: nuclear envelope; nuclear membrane; nucleoplasm; nuclear pore; endoplasmic reticulum membrane
Genetic constraint (gnomAD): Loss-of-function variants: 32 observed, 67.9 expected, observed/expected ratio (o/e) 0.47, 90% interval 0.35 to 0.63. The upper end of that interval is the gene's LOEUF score, 0.63, which puts it in group 2 of 6, group 1 being the genes least tolerant of losing a copy. Missense variants: 1,106 observed, 1,245.1 expected, observed/expected ratio (o/e) 0.89, 90% interval 0.85 to 0.93. Synonymous variants: 484 observed, 523.48 expected, observed/expected ratio (o/e) 0.92, 90% interval 0.86 to 1.
Homologues: Orthologues: chimpanzee POM121 (94% identical), macaque POM121C (91% identical), dog POM121C (72% identical), mouse Pom121 (67% identical), rat Pom121 (67% identical), zebrafish pom121 (31% identical), tropical clawed frog pom121 (23% identical), Drosophila melanogaster Nup153 (12% identical). Paralogues in human: POM121C (77% identical), POM121L2 (35% identical), NUP214 (24% identical), NPAP1 (20% identical), NUP153 (18% identical), POM121L12 (6% identical).